IL6 (interleukin 6)
Diseases named in the same sentence as IL6 in open-access papers (continued):
Sharing a sentence is not in itself a finding about the gene and the disease.
pancreatic cancer (continued). "Furthermore, a previous study on patients with biliary tract and pancreatic cancer patients reported high serum levels of various cytokines, including IL-6, in those with high spleen FDG uptake." (PMID 38627864, 2024). "In addition, WDR5 ablation effectively results in the downregulation of immune checkpoints (PD-1, PD-L1, and Spp1) and immunosuppressive cytokines (TGFβ and IL6) in pancreatic tumor microenvironments, leading to improved CD8+/CD4+ T-cell infiltration." (PMID 39201460, 2024). "This indicates that IL-6 contributes to the development of cachexia in pancreatic cancer." (PMID 38828409, 2024). "This study explored the correlation between pretreatment serum IL-6 levels, encompassing pro-inflammatory cytokine levels, and survival outcomes in advanced pancreatic cancer patients, while also assessing how these biomarkers influence the efficacy of systemic chemotherapy." (PMID 38672257, 2024). "Interestingly, Lorazepam, a selective GPR68 agonist, increased the expression of IL-6 through GPR68 in human PDAC CAFs and was associated with poor survival outcomes in pancreatic cancer." (PMID 39336742, 2024). "We observed that NT5E expression was associated with several gene sets linked to amoeboid migration and pancreatic cancer progression, such as transforming growth factor–β (TGF-β), KRAS, WNT, nuclear factor κB (NF-κB) and IL-6/JAK/STAT3 signaling, hypoxia, or EMT." (PMID 37851808, 2023). "In addition, combined blockage of IL6 and PD‐L1 signalings reduced pancreatic cancer progression in vivo, with the efficacy being clinically investigated (NCT04191421)." (PMID 36762766, 2023). "Moreover, IL-6 can lead to increased proliferation, invasiveness, and tumour progression in the pancreatic tumour microenvironment." (PMID 37760608, 2023). "Our previous study on tissue micro-arrays from a cohort of 175 patients with PDAC showed that STAT3, phosphorylated STAT3, and IL-6 were expressed in more than half of the examined pancreatic tumors, supporting the importance of this pathway in pancreatic cancer." (PMID 36495330, 2023). "In addition, YAP1 promotes the expression of IL‐6 through regulating immune reprogramming in pancreatic cancer." (PMID 37287755, 2023). "Moreover, the combination of IL-6 blockades and anti-PD-L1 antibodies reduced cancer progression in mouse pancreatic cancer." (PMID 37480115, 2023). "CAFs-derived IL-6 induced pancreatic cancer cell migration and invasion." (PMID 37480115, 2023). "IL‐6 is a known prognostic marker in both local and metastatic pancreatic cancer." (PMID 36250429, 2023). "For instance, IL-6 is an inflammatory cytokine secreted by iCAFs in response to paracrine signaling from the malignant epithelium, which leads to enhanced invasion and colony formation of pancreatic cancer cells." (PMID 37174079, 2023). "Again, for pancreatic cancer, IL-6 was the biomarker mentioned most frequently." (PMID 37181043, 2023). "Additionally, CAF-secreted IL-6 increased glycolytic flux in pancreatic tumor cells and lactate efflux in the microenvironment, favoring the activation of M2 macrophages in the TME and excluding CD8+ T cells." (PMID 37174079, 2023). "In addition, the activation of MAPK, PI3K-Akt, YAP-TAZ, and JAK-STAT3 signaling pathways by Kras in pancreatic cancer cells results in the upregulation of various suppressive cytokines and chemokines, such as IL-4, IL-6, IL-13, CSF1, and MCP-140,41." (PMID 37184030, 2023). "Among the 19 pancreatic cancer papers included in this review, IL-6 was mentioned in seven." (PMID 37181043, 2023). "Moreover, the dysregulation of IL-6’s downstream signals also plays an important role in the occurrence and development of pancreatic cancer." (PMID 37415745, 2023). "IL-6 also promoted the migration of pancreatic cancer cells in the presence of AR." (PMID 36834922, 2023).
pancreatic cancer (continued). "In pancreatic cancer, IL-6 induces the expression of Jagged-1/2 through Jak/STAT signaling, which enhances the expression of IL-6 mRNA in fibroblast cell lines through the NF-κB pathway to form a positive feedback loop and stimulates the production of platelets to form a hypercoagulable state." (PMID 37449201, 2023). "IL-6 enhances STAT3 phosphorylation in pancreatic cancer PANC-1 cell line." (PMID 36291659, 2022). "It is conceivable that persistently elevated plasma IL-6 levels promote pancreatic cancer cell survival and a pro-inflammatory tumor microenvironment, and mediate resistance to radiotherapy and chemotherapy, thereby negatively impacting survival of PDAC patients." (PMID 36551971, 2022). "IL-6 plays various roles in the progression of pancreatic cancer." (PMID 35493517, 2022). "In addition, the targeted inhibition of IL-6 has been reported to promote T cell infiltration and enhance the efficacy of ICIs to treat colorectal and pancreatic cancers in recent studies." (PMID 35550592, 2022). "For example, IL6 could promote the development and proliferation of pancreatic cancer cells through the STAT3–Pim kinase axis." (PMID 35401700, 2022). "We surmised that the increased CAFs induced by damp-heat syndrome might suppress the IL6 production of TAMs and drive pancreatic tumor growth by promoting desmoplasia, this complicated intercellular interaction remains intriguing to be explored." (PMID 35957897, 2022). "STAT3 pathway plays a role in pancreatic cancer, in which IL-6 is the driving factor." (PMID 36291659, 2022). "IL-6 gene knockdown sensitized pancreatic cancer cells to gemcitabine." (PMID 35626089, 2022). "Overall, these data suggest that serum miR-301a, in combination with examination of TGF-β and IL-6, might be a fibrosis marker for fibrosis in patients with chronic pancreatitis and early pancreatic cancer." (PMID 35211358, 2022). "In a different study, mice treated with pancreatic cancer cells lacking IL-6 expression exhibited less adipose tissue loss and were protected from muscular atrophy." (PMID 35159388, 2022). "Targeting IL-6 was suggested to be one of the therapeutic approaches for pancreatic cancer." (PMID 36140220, 2022). "High IL‐6 expression occurs in the stroma of pancreatic cancer." (PMID 35301813, 2022). "Similarly, IL-6 is elevated in both colorectal and pancreatic cancer (PC) patients and promotes proliferation and anti-apoptotic effects in CRC; further, IL-6 is correlated with advanced stages and poor survival of PC patients." (PMID 36139592, 2022). "Another potential mechanism could include the overexpression of interleukin-6, a pro-inflammatory cytokine, in the tumor progression of pancreatic cancer." (PMID 36432624, 2022). "Furthermore, it has been reported that murine cDC1s are systemically dysregulated early in pancreatic cancer and that apoptosis of cDC1s mediated by IL-6 essentially contributes to this effect." (PMID 35267524, 2022). "Finally, we demonstrated that PF inhibits IL-6 and IL-10 expression and p38 phosphorylation in pancreatic cancer cells, thereby reducing inflammation." (PMID 36339551, 2022). "Acupuncture affecting pancreatic cancer through TLR4/NF-κB/IL-6/STAT3 pathway may be a potential method for the treatment of pancreatic cancer." (PMID 36105933, 2022). "the activated IL-6/STAT3 pathway upregulated autophagy levels in pancreatic cancer cells." (PMID 35559037, 2022). "Targeting IL-6 in acupuncture treatment of pancreatic cancer is a promising research direction, which may involve IL-6/STAT3 axis, DNMT1-induced SOCS3 methylation, NRP-1, etc." (PMID 36105933, 2022). "Pancreatic cancer is a complex disease; it involves changes in cancer inflammatory components dominated by IL‐6,33 which may affect hyperactive delirium." (PMID 35880545, 2022). "Interestingly, serum levels of IL-6, IL-8, IL-10, and IL-1RA were significantly increased in pancreatic cancer patients." (PMID 36140220, 2022).
pancreatic cancer (continued). "Anti-IL-6 therapy as an adjuvant in combination with other targeted therapies may represent a novel area worthy of exploration in the treatment of pancreatic cancer." (PMID 34988078, 2021). "N4 abrogated IL-6-stimulated STAT3 phosphorylation in pancreatic cancer cells." (PMID 33420372, 2021). "Research has shown that transcription of PD-L1 is regulated by IL-6 in pancreatic cancer." (PMID 34988078, 2021). "Three-dimensional cultures of monocytes with spheroids containing pancreatic tumor cells and fibroblasts have been shown to increase the expression of immunosuppressive cytokines, such as IL-6 and macrophage colony-stimulating factor (M-CSF), known to induce MDSCs and M2-like macrophages." (PMID 34203869, 2021). "Our results suggest that ERβ signaling and IL-6/gp130 interaction may serve as promising drug targets for pancreatic cancer and that raloxifene may serve as an attractive therapeutic option for PDAC patients expressing the ERβ isotype." (PMID 32940862, 2021). "In a mouse model of pancreatic cancer, HPSE overexpression was associated with increased macrophage expression of M2 cytokines IL-6, IL-10, CCL-2, VEGF, and macrophage scavenger receptor-2 (MSR-2), increased tumor size, and increased levels of tumor-infiltrating macrophages." (PMID 34461608, 2021). "Furthermore, recent work shows that IL-6 contributes to systemic dysfunction of dendritic cells in pancreatic cancer, suggesting additional benefits of anti-IL-6 therapy." (PMID 34103524, 2021). "The TME in pancreatic cancer is composed of various types of cells that secrete abundant cytokines, including tumor cells, immunosuppressive cells, CAFs, inhibitory cytokines such as IL-6, IL-10 and TGF-β." (PMID 34290984, 2021). "However, high levels of serum IL-6, IL-8, and IL-10 are positive correlations with poor prognosis in pancreatic cancer." (PMID 33406733, 2021). "Furthermore, IL6 antibody blockade enhances the efficacy of anti-PD-L1 therapy in patients with pancreatic cancer." (PMID 34276760, 2021). "In addition, serum levels of IL-6 are higher in mouse models of pancreatic cancer (KPC) and PDAC patients." (PMID 34440697, 2021). "To test our hypothesis that IL-6 is responsible for the activation of the STAT3 pathway in pancreatic cancer cells, we performed experiments where we neutralized the IL-6 receptors (IL-6Rs) using the IL-6R neutralizing monoclonal antibody Tocilizumab." (PMID 34440697, 2021). "Similarly, pancreatic satellite cells (PSCs) undergo autophagy and produce IL-6 cytokine to promote pancreatic tumor growth, and the inhibition of autophagy in PSCs reduced IL-6 and decreased invasiveness." (PMID 33573362, 2021). "Particularly, some cytokines implicated in cancer-associated muscle wasting such as IL-6 and IL-1β are not elevated, consistent to a previous study in pancreatic cancer patients." (PMID 34950660, 2021). "Our previous results show that L-4F could inhibit pancreatic cancer progression, mostly by its anti-inflammatory effect, such as reduce the secretion of IL-6 in tumor tissue, While IL-6 could increase the infiltration of MDSCs in tumor tissue." (PMID 32425796, 2020). "IL6 has been shown to be involved in the progression of pancreatic tumors by others." (PMID 33177492, 2020). "IL6 induced metabolic reprogramming in pancreatic tumor cells." (PMID 33177492, 2020). "On the other hand, future studies are required to investigate whether interfering with the crosstalk between pancreatic cancer cells and SCs by targeting IL6 signaling could benefit patients with PDAC because of the inherent drawbacks of our animal model." (PMID 32308766, 2020). "Furthermore, in a iKRAS (p48-Cre;R26-rtTa-IRES-EGFP;TetO-KrasG12D) mouse model of pancreatic cancer, IL-6 appeared to be required for pancreatitis-driven PanINs formation." (PMID 32659999, 2020).
pancreatic cancer (continued). "Additionally, the stromal fibroblasts secrete IL6 as the major cytokine, increases glycolytic flux in the pancreatic tumor cells, and increases lactate efflux in the microenvironment via activation of the STAT signaling pathway." (PMID 33177492, 2020). "In this sense, IL-6 has shown contradictory results in non-fatty tissues, specifically bronchial epithelial cells, where the IL-6 overexpression decreases the autophagy, while in mouse myeloid cells and pancreatic tumor cells this interleukin favors autophagic flow." (PMID 33114725, 2020). "Furthermore, SC-derived IL6 induced pancreatic cancer cells migration and invasion via activating STAT3 signaling in vitro." (PMID 32308766, 2020). "Furthermore, in the pancreatic cancer patient population, increased expression of IL6 correlated with poor survival." (PMID 33177492, 2020). "Furthermore, our results show that the stroma secreted IL6 activates the STAT signaling pathway to enrich for “stem-like” CD133 + cells as well as alter the metabolic profile of the pancreatic cancer cells." (PMID 33177492, 2020). "Additionally, treatment with 1 μM Stattic in the presence of IL6 decreased glucose uptake as well as lactate production in pancreatic cancer cells Su86.86 and MIA-PACA2." (PMID 33177492, 2020). "Our data suggest that Cav-1 deficiency in PSCs is conducive to primary pancreatic cancer growth through upregulated paracrine cytokine signaling (including shh/MMP2/bFGF/IL-6) and that ROS play a vital role in the interaction between PSCs and pancreatic cancer cells." (PMID 32377291, 2020). "Interestingly, neither MIA PaCa-2 nor AsPC-1 cells cultured alone or co-cultured with SCs expressed detectable levels of IL6 mRNA, indicating that SCs educated by pancreatic cancer cells are the only source of IL6 in co-culture." (PMID 32308766, 2020). "Previously our group reported that Bazedoxifene could inhibit phosphorylation of STAT3 by targeting IL‐6/gp130 interface in pancreatic cancer cells, which implied the potential effect of Bazedoxifene on IL‐6/gp130 signalling in cardiovascular diseases." (PMID 32164044, 2020). "To understand whether LIF and IL-6 have different effects on the activation of YAP/TAZ-TEAD in pancreatic cancers, we treated serum-starved human pancreatic cancer cells with IL-6 or LIF at 100 ng/mL." (PMID 31296870, 2019). "Inhibiting the IL6/GP130/STAT3 pathway might therefore be a new therapeutic option for pancreatic cancer." (PMID 31139333, 2019). "Moreover, several critical inflammatory cytokines including TNFα, IFN-γ, IL-1α, and IL-6 were markedly increased within DMXAA-treated pancreatic tumors compared to control tumors." (PMID 31036082, 2019). "IL-6 is also highly expressed in serum from PDAC patients compared to non-diseased individuals and associated with disease aggressiveness and inflammatory response and pancreatic cancer-related cachexia." (PMID 31150430, 2019). "In pancreatic cancer, high expression levels of IL-6, a cytokine produced by a variety of cells including immune and pancreatic tumor cells, and IL-1β were correlated with poor overall and progression-free survival in pancreatic cancer patients." (PMID 31150430, 2019). "Then, the pancreatic cancer cells were incubated with various concentrations of IL-6 (0, 0.01, 1, 10 and 100 nM), and the CD59 expression and phosphorylation levels of STAT3 in cancer cells were significantly elevated to levels comparable to those in cells stimulated with THP-1 macrophages." (PMID 31685825, 2019). "Another case-control study nested in the European Prospective Investigation into Cancer and Nutrition (EPIC) cohort did also not find an association between pre-diagnostic circulating CRP, interleukin-6 (IL-6), tumour necrosis factors (TNF-α) and pancreatic cancer risk." (PMID 31464604, 2019). "Similarly, suppression of CAF mediated secretion of IL-6 by inhibiting mTOR pathway via somatostatin analogue reversed the chemoresistance in pancreatic tumor." (PMID 30680600, 2019).
pancreatic cancer (continued). "Since the literature reveals a poorer response to chemo-therapy when IL-6 is increased, evaluation of IL-6-levels might help in the development of personalized treatment strategies for patients with pancreatic cancer." (PMID 30038723, 2018). "In a murine study that combined anti-IL-6 and anti-programmed death-1-ligand in treating pancreatic cancer, a decrease in tumor weight was observed compared to the control group and mice treated with either drug alone, and the OS improved by 35% compared to the control group." (PMID 30038723, 2018). "Moreover, recent results demonstrating distinct sets of activated fibroblasts that either produce or respond to IL6 highlight the importance of stromal heterogeneity in promoting pancreatic tumor progression." (PMID 30456390, 2018). "More pancreatic cancer patients had elevated CA 19.9 than elevated IL-6." (PMID 30038723, 2018). "Additionally, activated PSCs play a vital role in the pancreatic cancer microenvironment by secreting molecules such as TGFβ, IL-6, stromal cell-derived factor-1 (SDF-1), hepatocyte growth factor (HGF) and galectin-1 to promote pancreatic cancer progression." (PMID 30060755, 2018). "Similarly, the level of inflammatory cytokines such as interleukin-6 (IL-6) was increased in carcinoma of the pancreas." (PMID 29662489, 2018). "It has already been tested in vitro on pancreatic cancer cells and it was shown to have equal or better effects than free curcumin on the human cancer cells, such as inhibition of NF-kB and down-regulation of interleukin-6 (IL-6)." (PMID 29029547, 2017). "Moreover, patients with pancreatic cancer with high IL-6 and IL-1β levels display low overall and recurrence-free survival after gemcitabine treatment." (PMID 28928376, 2017). "TTP over-expression influenced the expression of several tumor-related factors, and our results suggest that TTP may reduce pancreatic cancer cell proliferation and increase patient survival through downregulation of Pim-1 and IL-6." (PMID 26894969, 2016). "Given the already-reported roles of Pim-1 and IL-6 in pancreatic cancer tumorigenesis, we speculate that TTP may reduce cancer cell proliferation though downregulation of Pim-1 and IL-6." (PMID 26894969, 2016). "A more specific example of loss of EMT potential in the absence of IL-6 comes from pancreatic cancer." (PMID 27023622, 2016). "In addition to its role in the regulation of inflammation and immune response in PDA, we here show that IL-6 has a significant stimulatory effect on the proliferation, migration and invasion of pancreatic cancer cells." (PMID 27177087, 2016). "The importance and functionality of IL-6 secreted by CAFs was tested on pancreatic cancer cell survival, migration and invasion: 1 ng of recombinant IL-6 (rIL-6) stimulated the survival, migration and invasion of Panc-1 and BxPC-3 cells, although less efficiently than CAF secretions." (PMID 27177087, 2016). "CAFs from pancreatic tumors treated with retinoic acid have decreased expression of IL-6." (PMID 27023622, 2016). "IL-6 and IL-8, which may be secreted from tumor or stromal tissues, are hypoxia induced proteins, suggesting that pancreatic cancer may propagate through hypoxia signaling via HIF-1 alpha, though their role in promoting disease progression is unclear." (PMID 26808546, 2016). "Elevated serum levels of IL-6 are correlated with poor prognosis in pancreatic cancer patients." (PMID 25650658, 2015). "Moreover, it was recently shown that STAT-3 overexpression or STAT-3 activation by IL-6 significantly increased the levels of β-catenin in pancreatic tumor cells, and this effect inhibited β-catenin signaling." (PMID 26418031, 2015). "Moreover, the presence of an autocrine signaling loop between HIF-1a and STAT-3 was demonstrated in pancreatic cancer cell lines, where hypoxia mediates an increase in IL-6 production through HIF-1a leading to activation of STAT-3." (PMID 26517240, 2015).